MTOR (mechanistic target of rapamycin kinase)
Diseases named in the same sentence as MTOR in open-access papers (continued):
Sharing a sentence is not in itself a finding about the gene and the disease.
cancer (continued). "Moreover, the ability of Se NPs to promote cancer cell autophagy by activating ROS-mediated JNK pathway and inhibiting PI3K/Akt/mTOR pathway might also be combined with current chemotherapy method for synergetic anticancer treatment." (PMID 36819694, 2023). "It was recently reported that the mTOR pathway mediated the non-canonical Hh signaling cascade to induce PD-L1 expression, and that increased HH activity was a predictive biomarker for resistance to immune checkpoint inhibitors in diverse cancers." (PMID 37240209, 2023). "According to the results of the GSVA, M/PDA cells were mainly enriched in cancer-related signalling pathways contributing to tumour growth, proliferation, and metastasis, such as the epithelial-mesenchymal transition, E2F targets, PI3K/AKT/mTOR and KRAS signalling pathways." (PMID 37225691, 2023). "In addition to being a potent DNA-PK inhibitor, Nu-7441 has also been shown to inhibit PI3K, mTOR, and non-homologous end joining pathway, suggesting robust anti-cancer ability." (PMID 36878899, 2023). "The entry of the circulating CSC-regulating miRNAs into the cancer cells could potentially activate or inhibit various oncogenic signaling pathways, such as the PI3K/AKT/mTOR and WNT signaling pathway, and this would eventually affect cancer cell proliferation, invasion, and metastasis." (PMID 36674525, 2023). "Above all, everolimus, a pharmacological mTOR inhibitor widely used for advanced pNENs patient treatment, the lower expression of ALKBH5 may further synergize with everolimus to suppress mTOR activation and inhibit cancer cell growth." (PMID 37858219, 2023). "On the other hand, autophagy in cancer cells may exert dual roles, including contribute the antitumor effects and enhance the tumor progression; however, several anticancer drugs induce autophagy via the PI3K/Akt/mTOR signaling pathway." (PMID 36923503, 2023). "In cancer cells, HIF-1α may also be regulated by inducing high transcriptional and translational activity via different pathways: MAPK/ERK, JAK/STAT, and PI3K/AKT/mTOR." (PMID 36496973, 2022). "Based on the importance of this pathway in cancer progression and availability of targeted therapies against this pathway, therapeutic modalities that affect expression of TMPO-AS1 are promising strategies for enhancement of the effects of PI3K/Akt/mTOR-targeting modalities." (PMID 36467407, 2022). "Furthermore, several cancer-related pathways were significantly enriched in AFB1-infected chicken immune organs, such as the mTOR signaling pathway, VEGF signaling pathway, ErbB signaling pathway, and Toll-like receptor signaling pathway, which was consistent with previous studies." (PMID 36422982, 2022). "Early on, metformin’s role in cancer clearly showed that AMPK-dependent inhibition of mTOR is required for multiple anti-cancer effects, as the phenotype can be rescued by targeting AMPK with siRNA or Compound C as well as constitutive activation of mTOR and short hairpin RNA targeting TSC2." (PMID 35631452, 2022). "This positive correlation may indicate the critical role of UBE2C as a tumour oncogene during the cell cycle through enhancing the G1/S and G2/M transitions that prevent cancer apoptosis and promotes tumour cell proliferation via controlling the PI3K/AKT/mTOR signalling pathway." (PMID 35124721, 2022). "Recent evidence suggested that its upregulation may promote pan-cancer development by influencing cyclin genes and p38 MAPK, Wnt/β-catenin, PI3K/AKT/β-catenin, and Akt/mTOR autophagy signaling pathways." (PMID 36060253, 2022). "Considering that AKT/mTOR pathway has been well established to play a central role in the regulation of cell lipid metabolism, we hypothesized that ACLY overexpression may activate AKT/mTOR pathway to promote cancer development." (PMID 36064336, 2022). "Therefore, we suggest that the anticancer effects of lomitapide in cancer cells strongly implicate its engagement of mTOR and not MTTP." (PMID 35831271, 2022).
cancer (continued). "However, specific inhibition of Akt or mTORC1/mammalian target of rapamycin complex 2 (mTORC2) did not result in vacuolization, discarding the Akt/mTOR pathway as a player in the methuosis phenotype induced by JB in cancer cells." (PMID 35806262, 2022). "Notably, the response to AKT inhibitor VIII and RO-3306, which respectively target the PI3K/mTOR and cell cycle pathways, was consistent with the pan-cancer drug prediction results, but FH535 and BI-2536 did not appear in the results." (PMID 36059442, 2022). "Thus, we suggest that SNORA70E might regulate RAP1B and further regulates the expression of β‐catenin, PI3K, AKT1, mTOR, and MMP9 to exert cancer‐promoting effects." (PMID 36056690, 2022). "The anti-cancer activity of the combination of chemotherapy with vitamin C was mediated by AMPK (AMP-activated protein kinase) activation, which inhibited the signaling of the mTOR (mammalian target of rapamycin kinase) pathway closely related to cancer progression." (PMID 35215535, 2022). "Moreover, in some cancers of the BM2 sub-type the presence of PIK3CA mutations is not sufficient to activate the KRAS/AKT and mTOR/protein translation pathways." (PMID 36079062, 2022). "The correlation between the expression profile of proteins involved in the PI3K/AKT/mTOR signaling and cell viability in response to treatment with small molecule inhibitors targeting isoform-specific PI3Ks, AKT, and mTOR was assessed in 13 SCLC cancer cell lines." (PMID 35918763, 2022). "Importantly, in the present study, unlike other ATP-competitive, second-generation mTOR inhibitors, lomitapide was shown to exert anticancer effects on cancer cells with eIF4E overexpression." (PMID 35831271, 2022). "In this sense, it has been observed that there is an activation of mTOR induced by TGF-β and the PI3K-Akt pathway in cancer cells, which regulates endothelial cell growth and catalyzes the production of 3′-phosphorylated phosphoinositides enhancing cancer stem cells characteristics." (PMID 35745875, 2022). "Strong interconnection of PI3K-Akt-mTOR with another oncogenic pathway, RAS-RAF-MEK-ERK, the ability to activate MYC oncogene, and “druggability” of the downstream effectors and the adaptor proteins in this cascade make the PI3K-Akt-mTOR pathway an attractive target for cancer treatment." (PMID 36142768, 2022). "However, the mTOR pathway is not a cancer specific pathway and is widely used by non-cancerous cells as well." (PMID 35490242, 2022). "Furthermore, stigmasterol activated pro-apoptotic proteins, triggered PI3K/Akt, Akt/mTOR, and JAK/STAT, VEGFR-2 signaling pathways involved in numerous types of cancers and suppressed chemoresistance and enhanced inhibitory activity of some antiproliferative drugs." (PMID 36290632, 2022). "PI3K/Akt and mammalian target of rapamycin (mTOR; PAM) pathways are two signaling pathways that are necessary for many cellular activities, such as motility, proliferation, differentiation, metabolism, survival, and angiogenesis, in both normal physiology and development of cancer." (PMID 35986321, 2022). "Importantly, NOP56 knockdown sensitizes KRAS-mutant cancer cells to mTOR inhibitors in vitro and in vivo, which is not true for KRAS-wild-type tumor cells." (PMID 35039048, 2022). "In addition, the combination of GLUT inhibitors with GLUT signaling pathway inhibitors (e.g., Akt, mTOR, PI3K, HIF-1α, and AMPK) could be a new direction for cancer therapy." (PMID 36230492, 2022).
cancer (continued). "Furthermore, circRNAs can regulate multiple cancer-related signaling pathways, such as the microRNA sponges during HNSCC’s pathogenesis, involving EGFR, Notch, mTOR (mammalian target of Rapamycin), and MAPK (mitogen-activated protein kinase) signaling pathways." (PMID 35854245, 2022). "Cancer stem cells (CSCs) have higher mTOR and MLST8 fluorescence levels than non-CSCs." (PMID 36428613, 2022). "mTOR pathway plays multiple roles in cancer biology that may provides insights into cancer therapy, not limited to ICI treatment." (PMID 35642038, 2022). "Consequently, clinical trials are evaluating combination therapies with inhibitors against PI3K and MAPK signaling members, such as PI3K, AKT, mTOR, BRAF, and MEK, which are approved to treat different cancers as monotherapies or in combination with other agents." (PMID 35513296, 2022). "This may explain the general lack of efficacy of mTOR inhibitors in cancer clinical trials and argues against their widespread use in combination with DNA damage-inducing agents." (PMID 36396656, 2022). "In addition, mTOR has been recognized as a critical regulator of autophagy, and the AKT/mTOR pathway has also been widely reported to be related to autophagy in neurodegeneration and cancer treatment." (PMID 35620287, 2022). "It has been shown that the lack of miR-92a upregulates glycolytic and oxidative metabolism in cancer cells; however, the lack of miR-17 and miR-20a inhibits glycolytic and oxidative metabolism as well as mTOR pathways in cancer cells and increases the AMPK signaling pathway." (PMID 36292963, 2022). "While mTOR inhibitors alone do not induce cell death, they may sensitize cancer cells to cytotoxic therapies by disrupting NRF2 activity and cell defenses against oxidative stress and apoptosis." (PMID 35484114, 2022). "Indeed, this strategy may prove more effective by targeting distinct biological functions of cancer cells, such as DNA damage checkpoints (with SMYD3i) and cancer metabolism (with compounds targeting the AMPK/mTOR axis)." (PMID 35495117, 2022). "The perturbational class identified in our study, namely PI3K inhibitors, mTOR inhibitors, IGF-1 inhibitors, JAK inhibitors, DNA dependent protein kinase inhibitors, HDAC inhibitors, and FLT3 inhibitors, were also reported to mediate immune modulation in various cancers." (PMID 35954379, 2022). "In our results, we found an interesting phenomenon: compared with other cancer types, the mTOR pathway gene in KIRC mostly exists as a protective gene, which is inconsistent with previous research results that mTOR pathway overexpression can lead to the occurrence of cancer." (PMID 34194607, 2021). "IHC analysis on TMA showed that mTOR positive signal was distributed in majority of the adjacent non-tumor kidney tubule epithelial cells and sparse malignant cells, and p-mTOR positive signal was aggregately scattered in nonneoplastic kidney tubule epithelial cells and cancer cells." (PMID 34458019, 2021). "However, some cancers displaying constitutively active mTOR do not carry alterations within this canonical pathway, suggesting alternative modes of mTOR regulation." (PMID 34634301, 2021). "In LARP1-dependent cancer cells, LARP1 is phosphorylated by mTOR or by other pro-mitogenic kinases (such as CDK1 or AKT) and thus LARP1-mediated translational activation may be mTOR-dependent or independent." (PMID 32233986, 2021).
cancer (continued). "Therefore, our results support the hypothesis that LncRNAs are functional participants in therapy resistance/sensitivity to cancer drugs, and target‐gene therapies ‘EGFR/AKT/ERK/mTOR’." (PMID 33433063, 2021). "Notably, mTOR is stimulated independently of the P13K signalling pathway by CDK4, through the phosphorylation of tumour suppressor folliculin (FLCN) and promotion of lysosomal function, leading to increased cancer cell survival." (PMID 34828525, 2021). "mTOR inhibitors have been used as monotherapy or combination therapy in preclinical and clinical trials to test its efficacy in treating various cancers; however, the effects were marginal, suggesting that the full therapeutic potential of targeting mTOR has not been exploited." (PMID 35155187, 2021). "Concomitantly, the present study demonstrated for the first time that RAD001, an inhibitor of mTOR pathway, played a significant anti‐cancer role in ESCC by targeting the vascular system, which provides a possible target and drug choice for the treatment of this cancer type." (PMID 34120414, 2021). "The inhibition of the mTOR signaling pathway in tumors by zotarolimus reduced CD44, EGFR, TGF-β, and VEGF expression, which could decelerate the migration and invasion of tumor cells in cancer metastasis." (PMID 34361836, 2021). "The inhibition of the mTOR signaling pathway in tumors by zotarolimus reduced TGF-β, CD44, VEGF, and EGFR expression, which could decelerate tumor cell migration and invasion in cancer metastasis." (PMID 33925400, 2021). "This may explain why not every mTOR inhibition could induce diapause in mESCs or entry of cancer cells into dormancy, as a defined profile of mTOR regulation should be met in advance." (PMID 34832087, 2021). "Although inhibition of mTOR signaling promotes tumor cell death and several mTOR inhibitors have been used clinically, recent reports have shown that co-treatment with MHY1485, an mTOR activator, enhances the anti-cancer effects of anti-PD-1 antibody and 5-fluorouracil." (PMID 34265852, 2021). "As the proof of concept that if the combined inhibition of BET protein and mTOR signaling can be translated into the clinic, we also utilized a clinically relevant BET protein inhibitor OTX-015 (OTX, hereafter) which is currently in clinical trials for several advanced cancers." (PMID 34565342, 2021). "Overactivation of the mTOR pathway may affect the occurrence and development of cancer, but no specific treatment has been proposed for targeting the mTOR pathway." (PMID 34194607, 2021). "Of importance, HER3 is not detected in T cells, suggesting that HER3 may stimulate cancer-driving mTOR activity in HNSCC cells without modulating T cell function directly." (PMID 33888713, 2021). "Besides, our data showed that ADORA1 could activate EMT, Hormone ER, PI3K/AKT, RAS/MAPK, TSC/mTOR pathways and inhibit RTK, Hormone AR, DNA Damage Response, Cell Cycle, Apoptosis pathways to exert regulatory effects on the cancer process." (PMID 34093805, 2021). "However, cancer tissues expressed mTOR at significantly (p < 0.001) lower levels than adjacent normal tissues in KICH, KIRC, and KIRP; FGFR1 at lower levels in READ and THCA; and NOS2 at lower levels in KICH than adjacent normal tissues." (PMID 33842373, 2021).
cancer (continued). "Although mTOR (mammalian target of rapamycin), a well-known inhibitor of autophagy-dependent survival in physiological conditions, is also activated in KRAS mutants, many recent studies have revealed that autophagy becomes hyper-active in KRAS mutant cancer cells." (PMID 33925206, 2021). "Furthermore, we demonstrated that RBM11 affected the Akt/mTOR signaling pathway, which provides evidence and explanation why RBM11 could promote cancer cell progression." (PMID 34434291, 2021). "The use of mTOR inhibitors in cancer therapy did not provide the expected antitumor benefits." (PMID 33802831, 2021). "These pathways included the “transcriptional misregulation in cancer”, “pyrimidine metabolism”, “folate biosynthesis”, “MAPK signaling”, “Wnt signaling”, “phosphatidylinositol signaling system”, “T cell receptor signaling”, “axon guidance”, “insulin signaling”, and “mTOR signaling” pathways." (PMID 33627637, 2021). "Furthermore, other work has shown that MHY1485 may activate CD8+ T cells and promote follicular helper T cell differentiation via activation of mTOR, suggesting that MHY1485 may provide positive effects in anti-cancer immunity." (PMID 34265852, 2021). "In addition, some well-known cancer-related pathways, such as ‘focal adhesion’ (FDR = 3.35 × 10−3) and the ‘mTOR signalling pathway’ (5.68 × 10−3), were also enriched among our important genes, and focal adhesion kinase is reported to be a therapeutic target in OV." (PMID 34298802, 2021). "mTOR signaling activated protein synthesis by phosphorylating 4E-BP1 and S6K1; regulated metabolic pathways on transcriptional, translational, and posttranslational levels; promoted lipid and cholesterol synthesis; and was involved in autophagy, which was essential for the cancer progression." (PMID 34938313, 2021). "As a well-known mTOR effector, Maf1’s role in cancer radiosensitivity has not been investigated." (PMID 33640883, 2021). "In addition, these differentially expressed tRFs/tiRNAs may also participate in a variety of cancer-related signaling pathways such as FoxO signaling pathway, PI3K-Akt-mTOR signaling pathway." (PMID 33971811, 2021). "Given the available evidence on the role STAU1 in the control of two main autophagy regulatory pathways, mTOR and JNK, as well as its direct binding to ATG mRNAs, further studies are necessary to determine the exact role of STAU1 in autophagy control of normal and cancer cells." (PMID 34633481, 2021). "Thus, targeting P62 may be effective in some cancers, as demonstrated by the inhibition of P62 in bladder cancer that increases the sensitivity to the anti-cancer drug NVP-BEZ235, which also functions as an inhibitor PI3K/mTOR." (PMID 33573362, 2021). "For example, regulation of PI3K/Akt/mTOR signaling is a classic pathway involved in autophagy regulation, thus G-protein-coupled receptor antagonists, PI3K inhibitors, Akt inhibitors and mTOR inhibitors can inhibit this signaling pathway and induce autophagy in cancer therapy." (PMID 34512368, 2021).